Y_RNA (Y RNA )
Gene: Miscellaneous RNA gene on chromosome 7 (140,094,697 to 140,094,792, reverse strand). Ensembl gene ENSG00000251728.
Homologues: Orthologues: chimpanzee Y_RNA (99% identical), macaque Y_RNA (93% identical). Paralogues in human: Y_RNA (86% identical), Y_RNA (85% identical), RNY3 (84% identical), Y_RNA (84% identical), RNY3P1 (83% identical), Y_RNA (83% identical), RNY3P14 (82% identical), Y_RNA (82% identical), RNY3P11 (81% identical), Y_RNA (81% identical), Y_RNA (80% identical), RNY3P3 (79% identical), and 91 more.